JAK2 (Janus kinase 2)
Diseases named in the same sentence as JAK2 in open-access papers (continued):
Sharing a sentence is not in itself a finding about the gene and the disease.
ischemic stroke (33 papers, 2017 to 2026). A stroke disorder caused by obstruction of blood flow to the brain, due to thrombotic (local blood clot formation) or embolic (due to a blood clot or other material traveling from another site) event. "We report a 41-year-old man with low-risk PV (JAK2 V617F-positive) who presented 4 months later with an ischemic stroke and was incidentally found to have a 5.0 cm ascending aortic aneurysm." (PMID 42117004, 2026). "These cases, comprising four women and one man, represent a specific subset of individuals diagnosed with ischemic stroke and JAK2 mutation-associated ET." (PMID 37512112, 2023). "The Janus kinase 2 (JAK2) V617Fmutation is present in 60% of ET cases, and it has recently been reported that the mutation itself is a significant contributor to ischemic stroke." (PMID 38021556, 2023). "The overarching aim of this study is to enhance our understanding of ET, particularly in patients harboring the JAK2 mutation and experiencing ET-associated ischemic strokes." (PMID 37512112, 2023). "JAK2 is a major cause of ischemic stroke and associated with thrombosis." (PMID 36397023, 2022). "In another study about experimental ischemic stroke, secretoneurin protected neurons against hypoxic injury obviously by activating vascular regeneration Jak2/Stat3 pathway." (PMID 39002049, 2024). "The patient was admitted to the hospital with ischemic stroke, who was diagnosed with PV based on a Hb level of 187 g/L, HCT of 61.3%, and a positive JAK2/V617F mutation after admission." (PMID 38363912, 2024). "Previous research has shown that administering recombinant human Osm to mice before the initiation of ischemia/reperfusion can improve prognosis in mouse models of ischemic stroke by activating the JAK2/STAT3 signaling pathway in neurons." (PMID 36875640, 2023). "A previous study has shown that JAK2/STAT3 signaling pathways serve an important function in the downstream signal pathway regulation of ischemic stroke‐related inflammatory neuronal damage." (PMID 37786415, 2022). "Moreover, the JAK2/STAT3 signaling enhances recovery of neurological function after ischemic stroke." (PMID 40653468, 2025). "Given that the pro-angiogenic activities of ahNSCs are one of the treatment mechanisms for ischemic stroke, it was determined whether the JAK2/STAT3 signaling pathway is also involved in the pro-angiogenic activities of NSC-CM using endothelial cells (HUVECs)." (PMID 36446389, 2022). "Since C-C chemokine receptor type 2, a receptor of MCP-1, is closely associated with JAK2, MCP-1 could also be a key paracrine mediator that induces neuroprotective and pro-angiogenic activities of ahNSCs in the ischemic stroke models in this study." (PMID 36446389, 2022). "The aim of this study was to investigate whether inhibition of JAK2 has a neuroprotective effect on ischemic stroke and to explore the potential molecular mechanisms." (PMID 34367186, 2021). "Our study findings further suggest that not only Jak1, but also Jak2 may be involved in gliogenesis and astrocyte differentiation from neural stem cells after ischemic stroke." (PMID 31733648, 2019). "In order to determine whether pretreatment with a specific inhibitor of JAK2/STAT3 (AG490) would ameliorate the brain damage in ischemic stroke, we administered AG490 prior to tMCAO in Ntg and GET-1 mice." (PMID 31733648, 2019). "For instance, AD16 has been shown to mitigate ischemic stroke‐induced brain injury by reducing A1 astrocyte polarization, thereby suppressing neuroinflammation via the downregulation of NF‐κB and Janus Kinase 2 (JAK2)/signal transducer and activator of transcription 3 (STAT3) signaling pathway." (PMID 40130432, 2025). "Among them, there may be previously listed Fos, Junb, Jak2, Npas4, Egr2 and other proteins, which may help to validate some key signaling pathways after peptide treatment at the protein level and reveal the potential effects of peptides on ischemic stroke." (PMID 39767736, 2024).
ischemic stroke (continued). "As prothrombotic status with and without erythrocytosis in patients carrying JAK2 variants has been shown, this variant might be considered relevant in ischemic stroke etiology." (PMID 36411388, 2023). "LINGO-1 shRNA could ameliorate neurological deficits, reduce brain infarct volume and damage to cerebral cortical neurons in vivo ischemic stroke model, alleviate apoptosis and promote cell proliferation in vitro ischemic stroke model via the NF-κB and JAK2/STAT3 pathway." (PMID 33830473, 2021). "Its protective role is mediated through the inhibition of apoptosis and inflammatory responses via the JAK2/STAT3 axis, suggesting its potential as a therapeutic target for ischemic stroke." (PMID 41906531, 2026). "Our findings suggest that EP contributes to attenuating neuronal apoptosis, Th17/Treg imbalance, and inflammation induced by MCAO via inhibiting the JAK2/STAT3 pathway, indicating its therapeutic potential in ischemic stroke." (PMID 37143406, 2023). "The neuroprotective and pro-angiogenic activities of ahNSCs were mediated by paracrine factors and involved the JAK2/STAT3 signaling pathway in in vitro and in vivo ischemic stroke models in this study." (PMID 36446389, 2022). "Here, the present study revealed that LINGO-1 shRNA treatment suppressed the activation of the JAK2/STAT3 and NF-κB signaling pathways in both vivo and in vitro ischemic stroke models." (PMID 33830473, 2021). "In conclusion, our data suggest that shLINGO-1 attenuated ischemic injury by negatively regulating NF-KB and JAK2/STAT3 pathways, highlighting a novel therapeutic target for ischemic stroke." (PMID 33830473, 2021). "The results support the hypothesis that EP contributes to alleviating MCAO‐induced neuronal apoptosis, Th17/Treg imbalance, and inflammation via inhibiting the JAK2/STAT3 signaling pathway, indicating its therapeutic potential in ischemic stroke." (PMID 37143406, 2023). "Recently, Tian and his colleagues utilized real‐time quantitative reverse‐transcriptase polymerase chain reaction (qRT‐PCR) to test the JAK2‐related miRNA expression levels and western blot to analyze both OGD‐treated primary cultured neuronal cells and mouse brain with MCAO‐induced ischemic stroke." (PMID 37786415, 2022). "Additionally, HSYA may inhibit JAK2-mediated signaling, activating p-JAK2/p-STAT3 expression and subsequently suppressor of cytokine signalling-3 (SOCS-3), which provides negative feedback on p-JAK2/p-STAT3, aiding HSYA’s therapeutic effects on ischemic stroke." (PMID 40843199, 2025).
asthma (32 papers, 2009 to 2025). "As the JAK2/STAT3 pathway is preferentially activated by IL-6, prevention of IL-6/JAK2/STAT3 signaling may be associated with the anti-inflammatory effects of H. cuspidatus treatment of asthma." (PMID 35572723, 2022). "We hypothesized that the mechanism of ZKPC against asthma could be associated with JAK2/STAT3 pathway." (PMID 34608825, 2021). "This study highlights the critical role of the JAK2/STAT3-EPAS axis in asthma through a combination of bioinformatics analysis and experimental validation." (PMID 40165005, 2025). "The NLRP3 inflammasome also regulates ferroptosis in asthma inflammation through the JAK2/STAT3 pathway." (PMID 41550926, 2025). "Zisuzi Decoction ameliorates AHR and partially reverses airway remodeling through inhibition of PI3K/AKT1/mTOR, JAK2/STAT3, and HIF‐1α/NF‐κB signaling pathways, demonstrating effectiveness in cough‐variant asthma management." (PMID 41426510, 2025). "Janus kinase 2 (JAK2), a unique hub gene for DMP, is an important regulator associated with asthma inflammation." (PMID 40160461, 2025). "JAK2 is found to be related to goblet cell metaplasia during asthma, while the effects of additional factors on asthma need to be further explored." (PMID 39239069, 2024). "Considered together, m6A-YTHDF1 plays a complex role in the pathological process of inflammatory response in the NA asthma subtype through the regulation of the macrophage JAK2/STAT3 signaling pathway." (PMID 39108751, 2024). "While the involvement of JAK2 in goblet cell metaplasia in asthma has been established, the roles of other factors in this process are still unclear and require further investigation." (PMID 38078005, 2023). "Among our genes that were driven by rare variants, i.e., ALOX15, CSF2RB, IL17RA, IL33, JAK2, S1PR4, and SH2B3, previous studies supported a rare variant association between IL33, which is a known asthma locus, and eosinophil count." (PMID 35935937, 2022). "A more comprehensive understanding of the action mechanism of ZKPC on JAK2/STAT3 signaling pathway in human bronchial epithelial cells induced by IL-6 or M2 supernatant will enable ZKPC development in the control of asthma." (PMID 34608825, 2021). "Our study demonstrated that rhynchophylline can alleviate asthma through suppressing autophagy in asthma, and that JAK2/STAT3 signal was involved in this effect of rhynchophylline." (PMID 33413331, 2021). "JAK1 and JAK2 signaling pathways are involved in dysregulation in atopic dermatitis and asthma immune response and include Th2 response exaggeration, B-cell maturation, and activation of eosinophils." (PMID 34925353, 2021). "The phosphorylated JAK2 and phosphorylated STAT3 in the cells treated with TGF-β were increased compared with the control cells, indicating the activation of JAK2/STAT3 signaling in the in vitro model of asthma." (PMID 33413331, 2021). "The combined interaction scores resulted in higher interactions for the genes STAT3, AGO2, COL1A1, CLCN6, and KSR for moderate asthma and JAK2, INSR, ERBB2, NR3C1, and PTK6 for severe asthma." (PMID 32512817, 2020). "Notably, these findings highlight the JAK2/STAT3/EPAS1 axis as a potential therapeutic target for asthma, offering new insights into its molecular mechanisms and identifying novel biomarkers for diagnosis and treatment." (PMID 40165005, 2025). "Furthermore, it seeks to investigate the regulatory role of the JAK2/STAT3/EPAS1 axis in ferroptosis in asthma." (PMID 40165005, 2025). "Collectively, MEO may have an inhibitory effect on asthma under the condition of PM10 exposure through the IL-6/JAK2/STAT3 signaling pathway." (PMID 33374928, 2020). "For example, in severe asthma, the combined interaction scores for the STAT3, AGO2, COL1A1, CLCN6, and KSR1 genes yielded a higher interaction for the moderate asthma phenotype, and the JAK2, INSR, ERBB2, NR3C1, and PTK6 genes were more interactive for the severe asthma phenotype." (PMID 32512817, 2020).
asthma (continued). "Recent clinical validations indicate that inhibition of the JAK2/STAT6 signaling pathway may be considered for ovalbumin-induced asthma therapies." (PMID 32512817, 2020). "Both genes have a high correlation with asthma pathogenicity (>3.5 p-value (−log10)), where JAK2 and STAT3 were linked to moderate and severe asthma phenotypes and have a high number of pathogenic SNPs (8 and 24 SNPs, respectively) and related human diseases (18 and 37 diseases, respectively)." (PMID 32512817, 2020). "Similarly, JAK2 controls white blood cells, a number of red blood cells and platelets that are correlated with severe asthma." (PMID 32512817, 2020). "Peppermint oil would help to alleviate asthma by inhibiting the IL-6/JAK2/STAT3 pathway." (PMID 33374928, 2020). "We hypothesized that JAK2/STAT3 signal may mediate the effect of rhynchophylline on asthma." (PMID 33413331, 2021). "PTGS2, IL10, CTSB, JAK2, and MTOR were significantly downregulated in alveolar lavage fluid with increasing asthma severity, while MMP9, GSK3B, BCL2, EGFR, and CCND1 were upregulated." (PMID 40160461, 2025). "This study aims to better understand how the JAK2/STAT3/EPAS1 axis regulates inflammation and ferroptosis in asthma." (PMID 40165005, 2025). "Previous studies have shown that miR‐140‐3p can modulate the JAK2/STAT3 signaling by targeting HMGB1, reducing airway inflammation and remodeling in asthma." (PMID 40044625, 2025). "CIAPIN1 plays a role in the PI3K/AKT and JAK2/STAT3 signaling pathways, making it a promising candidate for therapeutic interventions to manage asthma." (PMID 40338178, 2025). "Notable genes that were differentially methylated based on asthma severity included RUNX3, several members of the HLA family, AGT, PTPRC, PTPRJ, and several genes downstream of the JAK2 and TNF signaling pathway." (PMID 39380119, 2024). "In this work we confirmed that LPS phosphorylates JAK2/STAT3, ERK1/2 and P38 in neutrophils from severe asthma and COPD patients which were attenuated by LAS194046, showing synergic inhibitory effects when combined with fluticasone propionate." (PMID 35332239, 2022). "Neutrophils from healthy subjects, severe asthma and COPD patients showed a higher expression of JAK2 followed by JAK3 and in a lesser extent of JAK1, while levels of TYK2 were the lowest." (PMID 35332239, 2022). "The LPS stimulation of human neutrophils from severe asthma and COPD patients increased the phosphorylation of JAK2 and STAT3 as well as the phosphorylation of ERK1/2 and P38." (PMID 35332239, 2022). "Thus could confirm the strong association of JAK2, STAT3 and severe asthma." (PMID 32512817, 2020). "In summary, IL-13 may promote ferroptosis and inflammation by activating JAK2/STAT3 and EPAS1, leading to 16HBE cell damage and potentially contributing to asthma progression." (PMID 40165005, 2025). "The JAK2/STAT3 signaling pathway in macrophages is an important target for allergic asthma development and is involved in important asthma pathological processes such as the activation of mast cells and the promotion of bronchial smooth muscle thickening and airway remodeling." (PMID 39108751, 2024). "The elevated levels of JAK2 and JAK3 in neutrophils from COPD and severe asthma patients could explain the efficacy of LAS194046 inhibiting IL-8 and MMP9 release, as well as the inhibition of ROS production that we observed." (PMID 35332239, 2022). "In this study, we revealed that rhynchophylline suppressed autophagy of ASMCs through inhibiting the JAK2/STAT3 signaling pathway, which may contribute to its therapeutic action on asthma." (PMID 33413331, 2021). "Furthermore, rhynchophylline suppressed the JAK2/STAT3 signaling pathway, which was activated in asthma." (PMID 33413331, 2021).
asthma (continued). "Moreover, there is an investigation to find the effects of PM2.5 on JAK2/STAT3 signaling pathway in human bronchial epithelial cells, giving the possibility of a therapeutic target for asthma by inhibiting the JAK/STAT signaling pathway under an air pollution-exposed condition." (PMID 33374928, 2020). "Patient also presented with secondary erythrocytosis (Haemoglobin 195, janus kinase 2 [Jak2] negative, with increasing erythropoietin [EPO] level), attributed to severe sleep apnea and asthma." (PMID 37206271, 2023).
bladder cancer (32 papers, 2012 to 2025). "Overexpression of the regulator Musashi-2 has been linked to JAK2/STAT3 activation in 34% of bladder cancer samples." (PMID 40277814, 2025). "Ox-LDL increase the association of CD36 with JAK2, resulting in increased bladder cancer dryness by promoting JAK2 phosphorylation and activating the STAT3 signaling cascade." (PMID 39290325, 2024). "In bladder cancer, PRDX6 promoted the proliferation and cell cycle of bladder cancer cells through JAK2/STAT3 signalling pathway." (PMID 38506082, 2024). "Conversely, increased expression of circRNA_0013936 has been reported to suppress bladder cancer cells by activating JAK2 and CREB1." (PMID 39628486, 2024). "EZH2 can promote the proliferation and migration of bladder cancer cells by activating JAK2/STAT3 signalling pathway." (PMID 38506082, 2024). "It has also been shown that JAK2 inhibitor can synergize with methylsulfonylmethane to curb the progression of bladder cancer." (PMID 35818076, 2022). "A previous study investigated the role of JAK2 signaling pathway in human bladder cancer E-J and 5637 cells." (PMID 35207737, 2022). "In this study, the downregulation of the JAK2/NF-κB pathway was found to be closely related to the anti-cancer effects of HPP-induced polarized macrophages on bladder cancer." (PMID 34034714, 2021). "The findings indicated that HPP inhibited the proliferation and progression of bladder cancer by the polarization of macrophages to M1 type, and JAK2/NF-κB pathway was downregulated in the process of anti-bladder cancer." (PMID 34034714, 2021). "Alterations in JAK1 were observed in 8% and in JAK2 in 15% of patients indicating, that these genes are frequently altered in bladder cancer." (PMID 32046095, 2020). "Previously, the JAK2 tyrosine kinase inhibitor AG490 has been tested in bladder cancer with positive results." (PMID 32046095, 2020). "Binding of IL-28A to IL-28AR1 induced the activation of ERK1/2, p38MAPK, and Jak/Stat (Jak2, Jak3, Stat1, Stat3, and Stat5) signaling pathways in bladder cancer cells." (PMID 22962576, 2012). "CCL5 is believed to promote the proliferation and metastasis of bladder cancer through the JAK2/STAT3 signaling pathway, which might suggest the reliability of finasteride in reducing the occurrence of BCa from the perspective of the immune microenvironment." (PMID 39944628, 2025). "In addition, EZH2 is highly expressed in bladder cancer, while JAK2/STAT3 signalling pathway is abnormally activated." (PMID 38506082, 2024). "JAK2/NF-κB pathways were downregulated in the anti-bladder cancer process of activated macrophages." (PMID 34034714, 2021). "Specifically, CXCL14 activates the CCR7/JAK2/STAT3 axis, leading to the upregulation of ERCC4 transcription, which promotes DNA damage repair in bladder cancer cells, thereby facilitating the development of chemoresistance." (PMID 40898244, 2025). "Bladder cancer (BCa) exhibits SULF2-mediated IL-8 secretion through β-catenin, inducing M2 macrophage polarization via the JAK2/STAT3 signaling pathway." (PMID 40959082, 2025). "Activated macrophages suppressed bladder cancer cell proliferation, regulated apoptosis, and inhibited migration and epithelial-mesenchymal transition (EMT) by downregulating the Janus kinase 2 (JAK2)/NF-κB pathway." (PMID 39885918, 2025). "Collectively, our results suggest that CAF-derived CXCL14 targets CCR7 in bladder cancer cells, enhancing ERCC4 transcription through JAK2/STAT3 activation and subsequently binding to the ERCC4 promoter region." (PMID 40898244, 2025). "We have also identified the activation of ERK1/2, p38MAPK, JNK, JAK1, JAK2, JAK3, Stat1, Stat2, and Stat3 in bladder cancer cells." (PMID 22962576, 2012). "Our results from bladder cancer cells indicate that IL-20 induced activation of ERK1/2 and Jak1, Jak2, Jak3, Stat1, Stat2, and Stat5." (PMID 22962576, 2012).
bladder cancer (continued). "For patients with hypercholesterolemic bladder cancer, serum ox-LDL can bind to CD36 and activate the JAK2-pSTAT3 pathway, thereby promoting the cancer stemness of bladder cancer, increasing cancer cell proliferation, and inducing epithelial-mesenchymal transition in vitro." (PMID 41281744, 2025). "A study investigating bladder cancer showed that AG490 could inhibit cell growth and invasion, as well as induce cell apotosis and cycle arrest by inhibiting the activation of the JAK2/STAT3 signaling pathway." (PMID 32641093, 2020).